CD177 (CD177 molecule)
Description:
In association with beta-2 integrin heterodimer ITGAM/CD11b and ITGB2/CD18, mediates activation of TNF primed neutrophils including degranulation and superoxide production. In addition, by preventing beta-2 integrin internalization and attenuating chemokine signaling favors adhesion over migration. Heterophilic interaction with PECAM1 on endothelial cells plays a role in neutrophil transendothelial migration in vitro. However, appears to be dispensable for neutrophil recruitment caused by bacterial infection in vivo. Acts as a receptor for the mature form of protease PRTN3 allowing its display at the cell surface of neutrophils. By displaying PRTN3 at the neutrophil cell surface, may play a role in enhancing endothelial cell junctional integrity and thus vascular integrity during neutrophil diapedesis.
Synonyms: HNA-2a; NB1 GP; PRV-1; NB1; PRV1; HNA-2; HNA2A
Tractability: Antibody: UniProt places it where antibodies can reach, with high confidence; its Gene Ontology location is reachable by antibodies, with high confidence; UniProt predicts a signal peptide or a membrane-spanning region.
Gene: Protein-coding gene on chromosome 19 (43,353,686 to 43,364,395, forward strand). Ensembl gene ENSG00000204936.
Subcellular location: Cell membrane; Membrane raft; Secreted; Cytoplasmic granule membrane; Cell projection, lamellipodium
Pathways (Reactome):
Hemostasis: Cell surface interactions at the vascular wall; Regulation of clotting cascade
Immune System: Neutrophil degranulation
Gene Ontology:
Molecular function: calcium-dependent protein binding; integrin binding; protease binding; protein binding
Biological process: cell adhesion; cell-cell adhesion; cell-cell junction maintenance; leukocyte cell-cell adhesion; neutrophil extravasation; neutrophil migration; positive regulation of neutrophil degranulation; positive regulation of superoxide anion generation; protein localization to cell surface; regulation of endocytosis; regulation of integrin-mediated signaling pathway
Cellular component: extracellular exosome; extracellular region; membrane raft; plasma membrane; plasma membrane raft; secretory granule membrane; tertiary granule membrane; specific granule membrane; lamellipodium
Genetic constraint (gnomAD): Loss-of-function variants: 34 observed, 29.06 expected, observed/expected ratio (o/e) 1.17, 90% interval 0.89 to 1.56. The upper end of that interval is the gene's LOEUF score, 1.56, which puts it in group 6 of 6, group 1 being the genes least tolerant of losing a copy. Missense variants: 475 observed, 387.45 expected, observed/expected ratio (o/e) 1.23, 90% interval 1.14 to 1.32. Synonymous variants: 172 observed, 155.64 expected, observed/expected ratio (o/e) 1.11, 90% interval 0.98 to 1.25.
Homologues: Orthologues: macaque CD177 (55% identical), pig CD177 (54% identical), dog CD177 (53% identical), mouse Cd177 (53% identical), rat Cd177 (50% identical). Paralogues in human: LYPD4 (17% identical), TEX101 (16% identical).
Diseases named in the same sentence as CD177 in open-access papers:
CD177 is named in the same sentence as 225 diseases in open-access papers, as found by Europe PMC text mining. Sharing a sentence is not in itself a finding about the gene and the disease. The quoted sentences say what the papers report.
breast carcinoma (34 papers, 2010 to 2025). "Our recent study demonstrated that CD177 is expressed by epithelial cells of breast cancer where its expression is associated with a better prognosis." (PMID 34599187, 2021). "CD177 is another protein associated with cell adhesion and migration, which is highly expressed by Treg cell subsets (10–50% of the total number of Treg cells in breast cancer)." (PMID 34868991, 2021). "Low level of CD177 expressed in epithelial cells of breast cancer and cervical cancer tissue predicts the poor prognosis." (PMID 41142798, 2025). "There was an average of 22.4% CD177+ Treg cells among TI Treg cells in breast cancer and of 16.8% in ccRCC." (PMID 34599187, 2021). "We further confirmed the superior suppression from CD177+ TI Treg cells from another 5 breast cancer specimens." (PMID 34599187, 2021). "The expression of Treg-related genes involving Treg-suppressive function was largely unchanged between CD177+ and CD177− TI Treg cells in human breast cancer or ccRCC, with slight elevation of ICOS, TIGIT, and CTLA4." (PMID 34599187, 2021). "CD177+ or CD177− TI Treg cells had similar expression of FOXP3 mRNA in 5 breast cancers based on a published RNAseq dataset (GSE89225)." (PMID 34599187, 2021). "About 22.4% CD177+ Treg cells among TI Treg cells in breast cancer and 16.8% in ccRCC." (PMID 41142798, 2025). "Notably, the functional role of CD177 expressed on tumor-infiltrating regulatory T cells and epithelial cells within tumors has also been found in breast cancer and renal clear cell carcinoma." (PMID 41142798, 2025). "Using dual-color IHC staining, we identified CD177- and FOXP3-double-positive cells in breast cancer sections (red arrow)." (PMID 34599187, 2021). "We found that CD177+ or CD177− TI Treg cells, defined as CD4+CD25+CD127low, from human cancer specimens exhibited a similar level of FOXP3 protein in 1 breast cancer, 2 colon cancers and 3 ccRCCs." (PMID 34599187, 2021). "To identify factors that can induce CD177 expression on Treg cells, we purified human PB Treg cells or CD4 Tconv cells from breast cancer patients, or splenic Treg cells or CD4 Tconv from MC38 tumor-bearing mice, either non-stimulated (ns) or treated with anti-CD3/CD28 and IL-2." (PMID 34599187, 2021). "One report from the Rudensky group identified CD177+ TI Treg cells in breast cancer with no further functional elaboration." (PMID 34599187, 2021). "Chemokine receptors on TI Treg cells were not significantly different between CD177+ and CD177− TI Treg cells from human breast cancer specimens, or between WT and Treg-KO TI-Treg cells from MC38 tumors." (PMID 34599187, 2021).
COVID-19 (33 papers, 2020 to 2025). A disease caused by infection with severe acute respiratory syndrome coronavirus 2. "Interestingly, CD177 has also been recently linked to COVID-19 severity." (PMID 38715615, 2024). "In severe coronavirus disease 2019 (COVID-19), which is characterized by an increase in neutrophils and inflammatory cytokines, it has been reported that CD177 levels in serum correlate with the severity of the disease." (PMID 39107780, 2024). "We detected significant up-regulation of CD177 expression in neutrophils from moderate and severe COVID-19 groups and a significant increase in overall percentages of CD177+ neutrophils." (PMID 36622345, 2023). "As leukocyte and platelet dysregulated functionality is observable, the neutrophil activation marker CD177 can also be used for assessment of COVID-19 severity." (PMID 35681519, 2022). "The patients with moderate COVID-19 had higher proportions of mature neutrophils, with higher expression of CD11b, CD66b, and CD177 than those with severe COVID-19 and the controls." (PMID 35456003, 2022). "In patients with COVID-19, high concentrations of CD66b, CD177, CD11b, CXCR4, CD147, and CD63, and low concentrations of CXCR2 were expressed on neutrophils." (PMID 35456003, 2022). "Comparison of severe and mild Symptomatic COVID-19 cases revealed an upregulation of CD177, the neutrophil marker, CXCL16, MAPKMAPK2 and IRF2BP2 with downregulation of ISGs; IFIT, IFIT3, OAS1, OAS2, LY6E and MX1 in severe cases." (PMID 34824360, 2021). "In severe COVID-19, CD177 a neutrophil marker, was upregulated while interferon stimulated genes (ISGs) were downregulated." (PMID 34824360, 2021). "CD177 is part of the granulocyte activation gene set and was indeed markedly increased in severe (day 1–10) compared to mild (day 1–10) COVID-19 samples." (PMID 33441124, 2021). "As depicted by the volcano plot, CD177, a member of the Ly-6 gene superfamily involved with neutrophil proliferation was the most upregulated in severe COVID-19 cases." (PMID 34824360, 2021). "Recent studies suggest that upregulated expression of granulocyte CD177 may serve as a potential marker for the physiopathology of COVID-19 in patients." (PMID 35418110, 2022). "In acute Kawasaki syndrome, elevated expression of CD177 was associated with resistance to treatment with intravenous immunoglobulin (IVIG), a therapy in COVID-19 patients that is currently investigated in clinical trials around the world (18 trials, clinicaltrials.gov)." (PMID 33441124, 2021). "Notably, a pronounced up-regulation of CD177 was observed on basophils from COVID-19 patients, and the magnitude of its expression was comparable to the expression of CD177 in CD16bright neutrophils." (PMID 34548411, 2021). "Both, severe and mild COVID-19 in comparison to controls shared neutrophil-specific CD177 and HP expression among the most upregulated DEGs, as well as lymphocyte-associated genes such as ABLIM1, NELL2, RCAN3, RORC, BACH2, and KLRB1, among the downregulated genes." (PMID 33441124, 2021). "Both moderate and severe COVID-19 patients were characterized by the progressive expansion of CD16dim neutrophils, which also expressed lower levels of CD177, CD11b, and CD62L and higher levels of CD66b and LOX-1, a phenotype compatible with neutrophil immaturity." (PMID 34548411, 2021). "Elevated concentrations of CD177 were recently identified by transcriptomics in the peripheral blood and by proteomics in BAL cells of patients with COVID-19 with mild and severe disease, which supports our data suggesting an upregulation of CD177 in the lung culture–positive decedents." (PMID 38226855, 2024). "Regarding neutrophils, the increased expressions of CD177, IL1R2 and S100A9 in our study agree with the existing literature, which points towards the induction of a dysregulated neutrophil function in COVID-19 patients with increased NET production that aggravates the pathophysiology of COVID-19." (PMID 36389738, 2022).
COVID-19 (continued). "We also observed significant up-regulation of CD66b, CD177, CD11b, CXCR4, CD147 (the receptor that binds the spike protein of SARS-CoV-2), and CD63 in mature neutrophils from COVID-19 patients compared to healthy controls, as well as significant down-regulation of CXCR2." (PMID 34548411, 2021). "Both moderate and severe COVID-19 patients were characterized by the progressive expansion of CD16 neutrophils, which also expressed lower levels of CD177, CD11b, and CD62L and higher levels of CD66b and LOX-1, a phenotype compatible with neutrophil immaturity." (PMID 34975885, 2021). "However, we did not explore the role of endogenous CD177 alterations in acute pancreatitis, which is a limitation of our study, due to the COVID-19 epidemic." (PMID 37048616, 2023).
Sepsis (33 papers, 2012 to 2026). Sepsis is defined as life-threatening organ dysfunction caused by a dysregulated host response to infection. "CD177 is a well-established marker of neutrophil activation and is closely associated with the hyperinflammatory phase of sepsis, consistent with previous studies indicating that neutrophil dysfunction contributes to systemic inflammation and organ failure." (PMID 40362669, 2025). "Meanwhile, based on the DEGs from two sepsis clusters, enrichment analysis reveals distinct pathways associated with CD177." (PMID 38332910, 2023). "This study concluded that CYSTM1, MMP8 and CD177 are pediatric sepsis diagnostic indicators." (PMID 37115484, 2023). "Additionally, CD177 showed significantly increased expression in sepsis patients, whereas IRAK3 is associated with the immune suppression stage." (PMID 38332910, 2023). "Notably, CD177 not only holds high diagnostic value for both IE and sepsis but also achieves good classification results in two distinct sepsis clusters with significant differences in immune cell populations." (PMID 38332910, 2023). "However, the precise role of CD177+ neutrophils, and association with sepsis and the extensive cellular damage that is seen in ACLF, need further investigation." (PMID 34552111, 2021). "CD177 is expressed primarily by neutrophils in the acute neutrophil response to an infection via neutrophil adhesion and transendothelial migration, and neutrophil CD177 mRNA levels are enhanced in numerous diseases associated with elevated neutrophil numbers, such as severe sepsis." (PMID 37115484, 2023). "CD177+ neutrophils are considered more activated than their CD177− counterparts and play a critical role in the immune response to infections, including sepsis." (PMID 40666706, 2025). "Our results align with studies showing that the activation of neutrophils, particularly CD177+ neutrophils, is crucial for sepsis development and its complications." (PMID 40666706, 2025). "A notable finding of our study was the high specificity of ZDHHC19 expression in CD177+ neutrophils, a subset of neutrophils involved in the pathogenesis of sepsis." (PMID 40666706, 2025). "We employed machine learning methods (LASSO, RF, and SVM-RFE) to select 3 diagnostic genes (CD177, LDHA, and MCEMP1) to investigate potential sepsis biomarkers." (PMID 39029061, 2024). "Machine learning algorithms identify 3 diagnostic genes - CD177, LDHA, and MCEMP1 - consistently highly expressed in sepsis patients." (PMID 39029061, 2024). "Using the rms package, we developed nomogram models for diagnosing pediatric sepsis based on the hallmark genes CYSTMI1, MMP8, and CD177." (PMID 37115484, 2023). "The results clearly show that the expression level of CD177 is significantly higher in sepsis samples than in normal samples." (PMID 38332910, 2023). "Numerous reports have indicated a definite link between the two hub genes, MMP8 and CD177, and the process of sepsis to some extent." (PMID 37115484, 2023). "In the GSE13904 validation set, the expression of CYSTM1, MMP8, and CD177 was considerably higher in the pediatric sepsis group than in the control group (P < 0.01)." (PMID 37115484, 2023). "Nineteen high-performance, differentially expressed mRNA biomarkers were identified between control and combined SIRS/Sepsis groups (FC>20.0, p<0.05), termed ‘indicators of inflammation’ (I°I), including CD177, FAM20A and OLAH." (PMID 38332914, 2023). "Beyond these confirmed genes, this study also discovered three potential diagnostic genes for IE (CD177, IRAK3, RNASE2) and one potential diagnostic gene for sepsis (RNASE2) for the first time." (PMID 38332910, 2023). "We successfully identified four key biomarkers correlated with IE and Sepsis, namely CD177, IRAK3, RNASE2, and S100A12." (PMID 38332910, 2023).
Sepsis (continued). "As pediatric sepsis diagnostic indicators, CYSTM1 (AUC = 0.988), MMP8 (AUC = 0.973), and CD177 (AUC = 0.986) were investigated and demonstrated statistically significant differences (P < 0.05) and diagnostic efficacy in the validation set." (PMID 37115484, 2023). "Increased CD177-expressing exhausted neutrophils are reported in several clinical conditions including sepsis." (PMID 35418110, 2022). "This is consistent with our findings, which also found that CD177 was significantly upregulated in sepsis patients." (PMID 35345523, 2022). "The relatively small-sized gelatinase-containing granule gene profile was dominated by increases in MMP9 and CD177 in both sepsis and SIRS." (PMID 35844509, 2022). "ELANE, MPO and CD177 were among the highest expressed genes in transcriptome meta-analyses of sepsis whole blood transcriptomes." (PMID 34552111, 2021). "Comparing the overall interaction responses of the immune-related clusters CD177, GPR84, and KLRK1, stimulatory responses were observed between KLRK1 and its associated genes in adult sepsis, adult SIRS, pediatric SIRS and pediatric resolved SIRS." (PMID 32318053, 2020). "There are few shared hub-associated entities between adult and pediatric Sepsis, with the exception of GPR84-associated EXOSC4 and ENTPD7, CD177-associated DDAH2 and MYL9-associated TGFB1l1." (PMID 32318053, 2020). "Similar profiles for GPR84 and CD177 were observed with the overlapped genes in sepsis (adult and pediatric–TDRD9) and in SIRS (adult compared with pediatric)." (PMID 32318053, 2020). "This set of data and our previous study underscored the powerful potential of using the real-time PCR method to determine the involvement of genes such as MPO, CD177, and NF-κB in infectious diseases like sepsis." (PMID 31428666, 2019). "Increased proportion of CD177+/PR3+ subpopulation of neutrophils is seen in AASV, SLE, as well as in states associated with increased granulupoiesis such as sepsis." (PMID 22403660, 2012). "For example, CD177 + neutrophils are increased in patients with sepsis, which may be a biomarker for assessing the severity of infection." (PMID 41142798, 2025). "The observation that ZDHHC19 was highly expressed in CD177+ neutrophils suggests that this subset may be particularly involved in the inflammatory processes of sepsis." (PMID 40666706, 2025). "In summary, CD177, LDHA and MCEMP1 were identified as diagnostic biomarkers for sepsis." (PMID 39029061, 2024). "Additionally, we discovered two Sepsis subgroups with distinct inflammatory responses and therapeutic strategies, where CD177 demonstrated significant classification value." (PMID 38332910, 2023). "There was association of TDRD9 with CD177 and GPR84 in adult and pediatric sepsis." (PMID 32318053, 2020). "Clustering of differentially expressed genes (DEGs) between control and sepsis samples showed significant differences, with significant up-regulation of CD177 and down-regulation of LOC440311, which may reflect a shift from hyperinflammation to immunosuppression." (PMID 40362669, 2025). "Furthermore, the high specificity of ZDHHC19 expression in CD177+ neutrophils suggests this enzyme may play a critical role in neutrophil activation and inflammation during sepsis." (PMID 40666706, 2025). "A total of 1389 DEGs such as NOV, SEPT9, XIST, ESYT1 were upregulated in sepsis, whereas 1657 DEGs such as S100A9, IRAK3, MCEMP1, TLR5, CD177 were downregulated." (PMID 41542228, 2026). "The cell percentage graph indicated that PADI4+ neutrophils, CD177+ neutrophils, and SNHG8+ neutrophils were significantly increased in sepsis tissues." (PMID 40666706, 2025). "Compared with those in healthy controls, the levels of CD177, SLPI, OLFM4, and LCN2 were elevated in plasma-EVs from patients with sepsis." (PMID 39901167, 2025). "The results revealed a significant up-regulation of MCEMP1, CD177, and LDHA in the sepsis groups compared to the healthy groups (P < .05)." (PMID 39029061, 2024).